NEIL3 (nei like DNA glycosylase 3)
Diseases named in the same sentence as NEIL3 in open-access papers (continued):
Sharing a sentence is not in itself a finding about the gene and the disease.
cervical cancer (1 paper, 2022). A primary or metastatic malignant neoplasm involving the cervix. "Recent studies have found that high levels of NEIL3 and circNEIL3 could promote carcinogenesis, metastasis and drug resistance in several ways, including HCC, NSCLC, GBM, cervical cancer and PDAC, and were strongly associated with poor prognosis of these cancers." (PMID 36497204, 2022).
Cirrhosis (1 paper, 2021). A chronic disorder of the liver in which liver tissue becomes scarred and is partially replaced by regenerative nodules and fibrotic tissue resulting in loss of liver function. "In the subgroup analysis, we found that for HCC patients with advanced TNM stage, poorly differentiated tumor, HBsAg positive or cirrhosis, and NEIL3 expression could serve as a prognostic factor." (PMID 34659404, 2021). "Furthermore, subgroup analysis showed that high NEIL3 expression predicted worse OS and DFS for HCC patients with advanced TNM stage, poorly differentiated tumor, HBsAg positive, or cirrhosis." (PMID 34659404, 2021). "Moreover, we found that HBsAg positive patients with high NEIL3 expression had worse OS (P=0.002) compared with HBsAg positive patients with low NEIL3 expression, and cirrhosis patients with high NEIL3 expression had worse DFS (P=0.004) compared with cirrhosis patients with low NEIL3 expression." (PMID 34659404, 2021).
head and neck squamous cell carcinoma (1 paper, 2022). A squamous cell carcinoma that arises from any of the following anatomic sites: lip and oral cavity, nasal cavity, paranasal sinuses, pharynx, larynx, and salivary glands. "We detected an upregulation of NEIL3 levels in higher grades in cancers such as KIRC, LGG, LIHC (liver hepatocellular carcinoma), PAAD, uterine corpus endometrial carcinoma (UCEC), and head and neck squamous cell carcinoma (HNSC)." (PMID 36612106, 2022).
kidney cancer (1 paper, 2022). Primary or metastatic malignant neoplasm involving the kidney. "NEIL3 showed a positive correlation with six types of immune cells in three cancer subgroups (pan-kidney cancer cohort (KIPAN, including KICH, KIRC, and KIRP), KIRC, and LIHC), involving B cells, CD8 T cells, CD4 T cells, DCs, macrophages, and neutrophils." (PMID 36612106, 2022).
metastatic cancer (1 paper, 2022). A carcinoma which has spread from the original site of growth to another anatomic site. "NEIL3 is highly expressed in various human cancer cells and is associated with metastatic cancer, indicating that it may be necessary to maintain cancer cell growth or malignant progression." (PMID 35308531, 2022).
ovarian carcinoma (1 paper, 2019). A malignant neoplasm originating from the surface ovarian epithelium. "For RFS of patients with ovarian cancer, SPOCK2 and FAXDC2 were unfavorable prognostic biomarkers but ADAMDEC1, CCNA2, FAM181A, FOXA2, LRRTM1, NEIL3 and XPR1 were favorable prognostic biomarkers." (PMID 31794425, 2019).
prostate tumors (1 paper, 2020). "We also found that somatic mutations in BRCA2, NEIL3, ATM, and ATR were associated with higher mutational burden in prostate tumors." (PMID 32300177, 2020).
Stroke (1 paper, 2025). Sudden impairment of blood flow to a part of the brain due to occlusion or rupture of an artery to the brain. "Loss of NEIL3 has previously been shown to impair in vitro expansion of adult NSPCs from the aged hippocampus and to affect stroke-induced neurogenesis." (PMID 40035863, 2025). "Our previous research has highlighted the important role of NEIL3 in various processes, including neural progenitor cell growth, post-stroke neurogenesis, hippocampal maturation, neuronal plasticity, and the hippocampus-dependent learning and memory." (PMID 40035863, 2025).
testicular germ cell tumor (1 paper, 2022). A germ cell tumor arising from the testis. "Regarding the immunosuppressive genes, NEIL3 is largely correlated with their upregulated expression in KIRC, KIRP, and LGG, while presenting a negative correlation regarding immunostimulatory genes in testicular germ cell tumors (TGCT), UCEC, and GBM." (PMID 36612106, 2022).
thymoma (1 paper, 2022). A neoplasm arising from the epithelial cells of the thymus. "Strikingly, in THCA and THYM (thymoma), NEIL3 was significantly associated with more than 20 immune checkpoint genes, such as CD86, ICOS, TNFSF4, and CD48, implying its role in regulating the tumor immune microenvironment." (PMID 36612106, 2022).
cancer (36 papers, 2009 to 2025). A tumor composed of atypical neoplastic, often pleomorphic cells that invade other tissues. "Our analysis illustrated that NEIL3 expression is associated with MSI in several cancers, such as STAD, SARC, and DLBC." (PMID 36612106, 2022). "NEIL3 can easily mutate and, consequently, increases the number of neoepitopes, which are more likely to be neoantigens in some cancers." (PMID 36612106, 2022). "The underlying mechanisms of NEIL3 in cancer have attracted extensive attention, making it an attractive therapeutic target for specific cancers." (PMID 35535347, 2022). "This study revealed that NEIL3 has a strong association with the immune microenvironment and phenotypic changes in selected types of cancers, such as KIRC, LIHC, and LUAD." (PMID 36612106, 2022). "Generally, NEIL3 expression is closely associated with the C1 (wound healing) and C2 (IFNγ-dominant) immune subtypes in a majority of cancers." (PMID 36612106, 2022). "It was reported that among the three types of drug-resistant cancer, the overexpression of NEIL3 was associated with a higher T/N stage and Gleason score, but it was positive with a good outcome for patients." (PMID 36497204, 2022). "Our results are consistent with those of Tran, who demonstrated that overexpression of NEIL3 is associated with unfavorable survival in selected types of human cancers." (PMID 36612106, 2022). "Recent studies have confirmed that the abnormal expression of NEIL3 was associated with the somatic mutation load in cancer." (PMID 35392496, 2022). "Concerning the fractional genome alteration of NEIL3 across cancers, the main mutation type was mostly missense mutations." (PMID 36612106, 2022). "Alterations of NEIL3 are also associated with somatic mutation loads, carcinogenesis, and poor survival in many human cancers." (PMID 34769200, 2021). "It was reported that the expression of NEIL1 and NEIL2 inversely correlated with the number of somatic mutations in several cancers, whereas NEIL3 showed a positive correlation." (PMID 32547565, 2020). "In conclusion, our data indicate that the alteration in NEIL3 function in cancer cells likely drives replication-associated genomic instability." (PMID 29348879, 2017). "Our studies demonstrated that HU-mediated dNTP pool depletion significantly increased cytotoxicity in NEIL3 deficient cancer cells, suggesting that the NEIL3 status of tumors should be routinely assessed to improve treatment response." (PMID 29348879, 2017). "We also showed that a subset of human cancers exhibited reduced NEIL1 and NEIL2 expression levels and an elevated NEIL3 expression level, and these abnormal expressions of NEIL1, NEIL2, and NEIL3 were associated with the mutation load in cancer." (PMID 27042257, 2016). "We found, for the first time, that the abnormal expressions of NEIL1, NEIL2, and NEIL3 are associated with somatic mutation loads in diverse cancers." (PMID 27042257, 2016). "Using a TCGA-based analysis, associations between abnormal NEIL1, NEIL2, or NEIL3 expressions and the somatic mutation load were apparently demonstrated in various cancer types for the first time." (PMID 27042257, 2016). "Collectively, NEIL3 presented a high mutation frequency among cancers." (PMID 36612106, 2022). "In accordance with our previous result, NEIL3 presented a high mutation frequency among cancers." (PMID 36612106, 2022). "In recent years, several studies have confirmed that abnormal expression of NEIL3 is closely associated with cancers and cardiovascular and neurological diseases, and it may be a potential prognostic molecule and therapeutic target." (PMID 36497204, 2022). "Furthermore, NEIL3 overexpression was associated with poorer overall survival (OS) in patients with these cancers." (PMID 36497204, 2022). "NEIL3 may be a potential prognostic marker for high-risk patients or an attractive therapeutic target for some cancers." (PMID 33644115, 2021).
cancer (continued). "Our results show that an inhibitor of PARP1 (Olaparib) sensitizes NEIL3 deficient cancer cells." (PMID 29348879, 2017). "Interestingly, the combination of ATR inhibitor with Olaparib synergistically sensitizes NEIL3 deficient cancer cells, suggesting that blocking the ATR-mediated DNA damage response synergizes the cytotoxicity of PARP1 inhibitor." (PMID 29348879, 2017). "We tested our hypothesis that NEIL3 is required to prevent oxidative and DNA replication-associated DNA damage, and that the loss of NEIL3-related DNA repair function in cancer cells alters the chemotherapy response." (PMID 29348879, 2017). "As such, the observed sensitization effect of both inhibitors utilized with NEIL3 deficient cancer cell lines may be related to the combined inhibition of both pathways." (PMID 29348879, 2017). "NEIL3 deficient cells are prone to oxidative DNA base damage, abasic sites, and strand breaks that likely offer an additional avenue to increased sensitivity in cancer cells." (PMID 29348879, 2017). "We suspect that this correlation may explain why the elevation in NEIL3 expression was associated with an increased number of somatic mutations in cancer." (PMID 27042257, 2016). "Finally, NEIL3 expression was shown to be correlated with the expression of APOBEC3B, a potent inducer of mutations, possibly explaining why an increased NEIL3 expression level was associated with the somatic mutation load in cancer." (PMID 27042257, 2016). "However, the association between the elevation in NEIL3 expression and the increased number of somatic mutations in cancer is surprising." (PMID 27042257, 2016). "We next investigated whether the abnormal expressions of NEIL1, NEIL2, and NEIL3 were associated with the mutation load in each cancer type." (PMID 27042257, 2016). "In addition, studies in recent years have revealed that NEIL3 and its epitope encoding source, circNEIL3, are overexpressed in various cancers and may act as an oncogene to promote cancer development and progression." (PMID 36497204, 2022). "In addition, NEIL3 is strongly associated with the progression of cancers and cardiovascular and neurological diseases, is incredibly significantly overexpressed in cancers, and may become an independent prognostic marker for cancer patients." (PMID 36497204, 2022). "However, the association between NEIL3, cancer prognosis, and immune response in LUAD is unclear." (PMID 33879165, 2021). "Finally, we investigated the reason why an elevated NEIL3 expression level was associated with an increased number of somatic mutations in cancer and found that NEIL3 expression was positively correlated with the expression of APOBEC3B, a potent inducer of mutations, in diverse cancers." (PMID 27042257, 2016). "Since migration and invasion are key hallmarks of cancer that drive tumor progression and metastasis, we investigated how NEIL3 and TOP2A influence these processes in EC cells." (PMID 39910812, 2025). "Among the SHRPI components, G6PD, HMMR, and NEIL3 were predominantly expressed in cancer cells, with G6PD showing the highest expression proportion." (PMID 41050691, 2025). "For instance, higher levels of CHD1L, HDAC1, MUTYH, NEIL3, POLR2L, RUVBL1, and SPP1 expression in cancer cells have been linked to higher levels of drug resistance to nelarabine, acridine, chlorambucil, dexrazoxane, cladribine, and other drugs." (PMID 37923899, 2023). "Remarkably, NEIL3 expression was positively correlated with all or part of the expression levels of these four DNA methyltransferase genes in pan-cancer, except for CHOL." (PMID 36612106, 2022). "In this review, we not only describe the structural specificity and functional specificity of NEIL3, but also focus on NEIL3 and circNEIL3 in cancer progression and prognosis." (PMID 36497204, 2022). "Our analysis showed that NEIL3 expression was negatively correlated with Th1 and Th17 cells and plasmacytoid DCs (pDCs), which are immunocytes that indicate a good prognosis in cancers." (PMID 36612106, 2022).
cancer (continued). "More importantly, we focus on the role and prognostic value of NEIL3 and circNEIL3 in cancer progression, which we hope will assist research into NEIL3 and cancer." (PMID 36497204, 2022). "Along with increased NEIL3 expression, the expression of most MHCII-encoding genes was decreased in most cancers." (PMID 36612106, 2022). "Given that neoantigens in different individuals of the same tumor show obvious individual heterogeneity, patients with different NEIL3 expression in various cancers should be categorized when considering neoantigen-specific therapy." (PMID 36612106, 2022). "Endonuclease VIII-like protein 3 (NEIL3) is a DNA glycosylase reported to be heightened in specific cancers." (PMID 36612106, 2022). "In our study, NEIL3 expression was related to an elevated level of TMB in a majority of cancer types." (PMID 36612106, 2022). "Pro-tumor chemokines, such as CXCL8, CXCL9, CXCL10, and CXCL11, can promote cancer cell proliferation and metastasis, and our results revealed that NEIL3 expression was positively correlated with them." (PMID 36612106, 2022). "Here, a pan-cancer landscape was presented to elucidate the characteristics of NEIL3 in the tumor microenvironment (TME)." (PMID 36612106, 2022). "Our results showed that the targeted chemotherapy was effective in cancer patients with higher NEIL3 expression, especially 1256580-46-7 in the CGP database, nelarabine in the CTRP database, and sorafenib in the CCLE database." (PMID 36612106, 2022). "On the contrary, anti-tumour chemokines, such as CCL14 and CX3CL1, were related to low NEIL3 expression in most cancers." (PMID 36612106, 2022). "NEIL3 expression was significantly related to all or part of the five MMR genes in pan-cancer, except for CHOL." (PMID 36612106, 2022). "For this reason, we evaluated the relationship between NEIL3 expression and the mutation levels of five critical MMR genes across cancers." (PMID 36612106, 2022). "A previous study showed that the expression level of NEIL3 was significantly higher in 16 cancer tissues than in normal tissues, except for testicular and pancreatic cancer tissues." (PMID 36497204, 2022). "In contrast, NEIL3 expression was significantly associated with active CD4 T cells and Th2 cells, which implies cancer recurrence in most tumors." (PMID 36612106, 2022). "Combined with prognosis analysis, which showed that higher NEIL3 expression contributes to poorer clinical outcomes, the potential of NEIL3 as an oncogenic predictor in cancer was revealed." (PMID 36612106, 2022). "As the grade of tumor-infiltrating lymphocytes is valued as an independent predictor of patient prognosis, immunocyte infiltration, along with diverse NEIL3 expression, was investigated in 33 cancer types." (PMID 36612106, 2022). "The mutation characteristics, survival patterns, and immune features of NEIL3 across cancers were analyzed." (PMID 36612106, 2022). "Taken together, the results indicated that NEIL3 is abnormally heightened in a majority of cancers, indicating its possibility as an oncogene." (PMID 36612106, 2022). "Generally, higher NEIL3 expression predicts poorer prognosis in cancer patients, suggesting its possibility as a prognostic indicator." (PMID 36612106, 2022). "With the aim of enhancing the understanding of NEIL3 in prognosis prediction and therapy administration, we conducted a pan-cancer landscape analysis on NEIL3." (PMID 36612106, 2022). "Our results revealed that NEIL3 was upregulated in tumor tissues, indicating its wide-range expression across cancers." (PMID 36612106, 2022). "Nevertheless, there is no integrative study reporting the immunological features of NEIL3 among cancers." (PMID 36612106, 2022). "The results of the paired tumor and adjacent cancerous samples showed that NEIL3 was heightened in 16 types of cancers, with sufficient paired samples at mRNA level." (PMID 36612106, 2022).